BCL2 (BCL2 apoptosis regulator)
Diseases named in the same sentence as BCL2 in open-access papers (continued):
Sharing a sentence is not in itself a finding about the gene and the disease.
bladder cancer (138 papers, 1999 to 2026). "Antiapoptotic protein BCL-2 and the proliferative protein ki-67 have also been linked to aggressive bladder carcinoma." (PMID 39250522, 2024). "BCL-2 overexpression is associated with poor prognosis, early recurrence of bladder cancer, and resistance to gene therapy and chemotherapy." (PMID 36289714, 2022). "This study showed that bcl-2, or loss of apoptotic potential, increases steadily with bladder chronic inflammation and with bladder cancer favoring SBT on NSBT." (PMID 19243595, 2009). "Furthermore, a JNK/Bcl-2/Beclin-1-mediated mechanism is associated with autophagy and apoptosis in bladder cancer cells." (PMID 30103466, 2018). "The results showed that compared with normal tissues, ESR1, PTGS2 and BCL2 in bladder cancer tissues were significantly down-regulated; CASP3, INS, SRC, CDK4, GSK3B and ERBB2 were significantly up-regulated." (PMID 41287122, 2025). "Collectively, these results suggest that β-sitosterol induces apoptosis in bladder cancer cells by modulating the BCL-2/Bax/Caspase-3 signaling axis." (PMID 41256326, 2025). "This study demonstrates that β-sitosterol, a major bioactive compound of nutmeg, suppresses bladder cancer progression by modulating the BCL-2/Bax/Caspase-3 axis and PI3K-Akt signaling pathway." (PMID 41256326, 2025). "The increased apoptosis is likely tied to the observed downregulation of anti-apoptotic genes like BCL-2, which is fully in agreement with the findings in bladder cancer cells." (PMID 39851519, 2025). "Studies have identified the overexpression of the Bcl-2 protein as a key factor contributing to cisplatin resistance in human bladder cancer cells." (PMID 39820585, 2025). "β-sitosterol, identified as a core bioactive compound, significantly suppresses the proliferation and migration of bladder cancer cells and induces apoptosis by modulating the BCL-2/Bax/Caspase-3 axis." (PMID 41256326, 2025). "Similar data were reported in the 5637 bladder cancer cell line in which the AgNPs induced excessive ROS formation, up-regulation of Bax/Bcl-2 expression, and caspase 3 and 7 activation." (PMID 39126001, 2024). "Higher levels of pro-apoptotic Bax and Noxa were observed in TTC, anti-apoptotic Bcl-2 was solely expressed in bladder cancer cells." (PMID 37891379, 2024). "It has been implicated in various cancers, such as bladder cancer, and in CRC, where it interacts with genes such as BAX and BCL2." (PMID 39408697, 2024). "In bladder cancer, inhibiting BCL-2 expression reduces cell proliferation and increases the sensitivity of cells to chemotherapy." (PMID 38930984, 2024). "Increased expression of BCL-2 is present in various types of tumors, including bladder cancer, supporting its tumorigenesis." (PMID 38930984, 2024). "The discovery in the present study that JorA increases Bid expression and decreases Bcl2, Bcl-XL, and Pax8 expression suggests that JorA accelerates the apoptosis of bladder cancer cells from multiple angles." (PMID 37587470, 2023). "Chitosan‐hyaluronic acid dialdehyde (HAD) nanostructures can deliver Bcl‐2‐siRNA to bladder cancer site and enable the suppression of tumor growth." (PMID 36684065, 2023). "Baicalein induces apoptosis in bladder cancer cells by increasing intracellular ROS and Bax protein expression and decreasing Bcl-2 expression." (PMID 38086844, 2023). "By increasing the internalization of siRNA in bladder cancer cells, the nanostructures reduced Bcl‐2 expression to suppress viability of tumor cells." (PMID 36684065, 2023). "Western blotting indicated that the expressions both of Bax and Casepase 9 were robustly elevated, whereas that of Bcl2 was decreased in gypenoside-treated bladder cancer cells compared to that in the control groups." (PMID 35402614, 2022).
bladder cancer (continued). "Bcl-2 overexpression in bladder cancer has been also reported to play an important role in cisplatin resistance." (PMID 36685879, 2022). "Yi Li and colleagues reported that thymol downregulated the Bcl-2 and Bcl-xl expression while it upregulated the P21 expression in bladder cancer cell lines." (PMID 35879400, 2022). "MiR-21 overexpression has been shown to increase Bcl2 expression and enhance Akt phosphorylation to promote cell proliferation in bladder cancer cells." (PMID 36685879, 2022). "Taking advantage of antisense oligodeoxynucleotides (AS-ODNs) to downregulate BCL-2 can partially sensitize bladder cancers to cisplatin and radiotherapy." (PMID 36289714, 2022). "Bladder cancer cells have a higher expression of anti-apoptotic proteins Bcl-2 and Bcl-xL and the increased expression of these anti-apoptotic proteins correlates with poor prognosis in bladder cancer patients." (PMID 36685879, 2022). "Inhibition of FAS leads, however, to reduced endogenous bcl-2 levels, as demonstrated in bladder cancer cells." (PMID 34483846, 2021). "Costunolide dose-dependently inhibits cell viability, induces apoptosis, downregulates Bcl-2 and survivin expression, activates caspase 3, and elevates Bax expression in T24 bladder cancer cells." (PMID 33996570, 2021). "Bax is a vital homologue of Bcl-2, an enhancer of apoptosis, and can be used as an independent parameter for predicting the clinical prognosis of individuals with bladder cancer." (PMID 33855047, 2021). "Mechanistic studies reveal that TR4 functions by altering the expression of Bcl-2 to regulate apoptosis in bladder cancer cells." (PMID 34616769, 2021). "Our rescue experiments also showed that overexpression of Bcl-2 partly rescued the proliferation ability, suggesting that Bcl-2 was an important downstream factor in bladder cancer prognosis." (PMID 34616769, 2021). "The expression levels of BAX and BCL-2 are similar to those in human bladder carcinoma cells exposed to Brazilian red propolis." (PMID 34083947, 2021). "Inhibition of FAS, on the contrary, leads to reduced endogenous bcl-2 levels, as demonstrated in bladder cancer cells." (PMID 34483846, 2021). "Ethanol extracts of pomegranate fruit (PEE) induced apoptosis by cleaving Cas-3 and raising Bax/Bcl-2 ratio in urinary bladder cancer T24 cells." (PMID 34356350, 2021). "Bax, an important homolog of Bcl-2, is a promoter of cell apoptosis and serves as an independent parameter to envisage clinical outcome for patients with bladder cancer." (PMID 33537343, 2020). "The silencing of this enzyme in bladder carcinoma cells led to a reduction in the levels of metalloproteinases and the Bcl-2 apoptosis regulator, consequently decreasing invasion activities." (PMID 33335138, 2020). "We further validated in bladder cancer Umuc-3 and 5637 cells that phosphorylation of Bcl2, Bad, and FoxO1 was consistently repressed by PPARγ agonist rosiglitazone, but enhanced by the inverse agonist T0070907." (PMID 30845932, 2019). "In this study, JNK activation triggered autophagy of bladder cancer cell through dissociation of the Bcl-2/Bcl-xL–Beclin-1 complex following C-2 treatment." (PMID 31685029, 2019). "A previous study reported that antrocin, a sesquiterpene lactone isolated from A. cinnamomea, induces apoptosis in human bladder cancer cells via a Bcl-2-dependent pathway and caspase-3 activation." (PMID 30914735, 2019). "In the present study, protosappanin B decreased Bcl-2 protein levels and increased Bax protein expression, leading to the increased apoptosis of bladder cancer cells." (PMID 30705351, 2019).
bladder cancer (continued). "Signal-connectors suppressing the human c-Myc gene and the BCL2 gene were generated as before and stably transfected into either bladder cancer cells or normal dermal fibroblasts." (PMID 29319503, 2018). "Among them, the bcl-2 and caspase families are well-known important regulators of apoptosis in many types of cancer cells, including bladder cancer cells." (PMID 30103466, 2018). "Long noncoding RNA HNF1A-AS1 (HNF1A antisense RNA1) acted as a ceRNA for miR-30b-5p to promote proliferation and suppress apoptosis of bladder cancer cells through upregulating Bcl-2." (PMID 30149689, 2018). "Our study demonstrated that hnRNP-L down-regulation resulted in the apoptosis of bladder cancer cells due to activation of apoptosis inducing factors, caspase-3/6/9 and suppression of apoptosis inhibitory factors, Bcl-2, Bcl-xL and PARP1." (PMID 28088793, 2017). "Bcl-2 modulates multi-drug resistance in bladder cancer cells and correlated with patient response to chemotherapy." (PMID 28178653, 2017). "The Bax-Anti Bcl2 combination module can effectively inhibits the malignant phenotypes of bladder cancer." (PMID 26743236, 2016). "Downregulation of antiapoptotic proteins Bcl-2 and Mcl-1 by Hd-Sb in bladder cancer cells was also observed." (PMID 26989427, 2016). "Compared with the negative control, the cell proliferation was significantly suppressed in bladder cancer 5637 cells and T24 cells transfected with artificial hTERT promoter-Bax-Anti Bcl2 combination module (P < 0.05)." (PMID 26743236, 2016). "Our results demonstrated that the Bax-Anti Bcl2 combination module driven by artificial hTERT promoter selectively inhibits malignant phenotypes of bladder cancer cells." (PMID 26743236, 2016). "In brief, the Bax-Anti Bcl2 combination module driven by artificial hTERT promoter selectively suppresses malignant phenotypes of bladder cancer cells." (PMID 26743236, 2016). "It indicates that the combination of Bax protein and anti-Bcl2 molecule can be used to reverse the ratio of Bcl2/Bax in bladder cancer." (PMID 26743236, 2016). "Exosome-derived microRNA29c induces apoptosis in bladder cancer cells by down-regulating BCL-2 and MCL-1." (PMID 27517627, 2016). "Induced cell apoptosis was observed in bladder cancer 5637 cells and T24 cells transfected with artificial hTERT promoter-Bax-Anti Bcl2 combination module." (PMID 26743236, 2016). "To analyze the potential therapeutic relevance of Bcl-2-targeted therapy and mechanisms promoting cell death resistance in chemoresistant bladder cancer, we established cisplatin- and gemcitabine-resistant cell lines." (PMID 25885284, 2015). "Anti-apoptotic members such as Bcl-2, Bcl-xL, Bcl-w and Mcl-1 are highly overexpressed in many malignancies including bladder cancer are known to adversely affect chemosensitivity and radiosensitivity." (PMID 25885284, 2015). "In this study, we confirmed that JS-K increases levels of cleaved caspase-9 and PARP proteins in bladder cancer cells but decreases the level of Bcl-2 protein." (PMID 26458509, 2015). "Theratio of Bcl-2 to Bax as its inhibitory homologuehas been considered to be more importantbiologically in bladder cancer than Bcl-2expression alone." (PMID 24381861, 2014). "At least, as just described in other studies, they confirmed how curcumin abolishes the constitutive activation of NF-κB in the tumor tissue; decreases cyclin D1, VEGF, COX-2, c-myc, and Bcl-2 expression in the bladder cancer tissue; and induces apoptosis." (PMID 24901005, 2014). "In this study it is shown that the Bcl-2/Bax expressionratio reveals bladder carcinomas with apropensity for relapses, tumor grade and stage." (PMID 24381861, 2014).
bladder cancer (continued). "Another line of evidence is that overexpression of Stat3-regulated anti-apoptotic genes (Bcl-2, Bcl-xL and survivin) is found in bladder cancer." (PMID 18939995, 2008). "In the bladder carcinoma explants, Bcl-2 expression was found to be 100% positive both in the presence and absence of l-deprenyl or clorgyline." (PMID 14612913, 2003). "Moreover, bladder cancer cells often resist infection-induced apoptosis, partly due to increased BCL2 expression, which allows them to persist in inflammatory environments triggered by infection, further promoting tumor proliferation and invasion." (PMID 41601648, 2026). "Further investigations into the role of CD44v3 in apoptosis regulation unveiled that the knockdown of CD44v3-containing isoforms mediates the reduction of PI3K, pAKT, pERK, pSTAT3 and Bcl2 protein levels, triggering apoptotic signaling and G0/G1 phase arrest in bladder cancer cells." (PMID 40114966, 2025). "Therefore, the overexpression of Bcl-2 has a key role in bladder cancer progression and aggressiveness." (PMID 38072891, 2024). "Studies show that the concentration of Bax and Bcl-2 can predict bladder cancer treatment outcomes." (PMID 37895809, 2023). "can induce apoptosis in cancer cells via the activation of pro-caspases and pro-apoptotic Bax and the inactivation of the anti-apoptotic Bcl-2 proteins, which may reduce chemotherapy toxicity and thereby might inhibit the progression of bladder cancer." (PMID 36005168, 2022). "Besides, bladder cancer cell-derived exosomes inhibit tumor cell apoptosis and promote cell proliferation in vitro, accompanied by elevated Bcl-2 expression and limited protein expression of Bax and caspase-3 with the increase of EV concentration." (PMID 35821021, 2022). "In advanced bladder cancer, quantifying BCL-2 may help select target patients who may benefit from neoadjuvant chemotherapy." (PMID 36289714, 2022). "Moreover, the miR-221 regulates Bcl-2 and BAX proteins, enhances the BAX protein level, and inhibits Bcl-2 while silencing the miR-221 in bladder cancer." (PMID 36232606, 2022). "Small interfering RNA (siRNA) targeting BCL-2 may help reverse cisplatin resistance in bladder cancer." (PMID 36289714, 2022). "Moreover, we demonstrated that TR4 promotes bladder cancer progression by upregulating the Bcl-2 expression." (PMID 34616769, 2021). "In addition, it caused chromatin concentration and nuclear fragmentation, thereby inducing bladder cancer cell apoptosis by the downregulation of Bcl-2 expression and upregulation of Bax and caspase-3 expression." (PMID 33996570, 2021). "The knockdown of Bcl-2 in overexpressing TR4 bladder cancer cells abolished the proliferation." (PMID 34616769, 2021). "It has also been found that bladder cancer cell-derived exosomes can induce cell proliferation and inhibit tumor cell apoptosis in vitro in conjunction with upregulated expression levels of Bcl-2, but reduced expression levels of Bax and caspase-3, which is in line with our current observations." (PMID 33423167, 2021). "Promisingly, we found that up-regulation of PAWR by saRNA inhibited the growth of bladder cancer cells by inducing cell apoptosis and cell cycle arrest which was related to inhibition of anti‐apoptotic protein Bcl-2 and inactivation of the NF-κB and Akt pathways." (PMID 34220332, 2021). "In MEG3 overexpressing bladder cancer, cisplatin could significantly induce cell apoptosis, down-regulate bcl2 expression and up-regulate cleaved-caspase-3 and bax expression." (PMID 31488093, 2019).
bladder cancer (continued). "Other reasons for the overexpression of pro-survival Bcl-2 members include gene amplification (e.g., diffuse large B-cell lymphomas), chromosomal translocation (e.g., Hodgkin’s lymphoma), and alterations in promoter methylation (e.g., bladder cancer)." (PMID 30875757, 2019). "In addition to inducing Bax, caspase-3 and PARP cleavage in T24 bladder cancer cells, costunolide also attenuated expression of survivin and Bcl2 as a mechanism of apoptosis induction." (PMID 31208018, 2019). "Thus, HNF1A-AS1 positively regulated the expression of Bcl-2 through sponging miR-30b-5p, and played an important regulatory role in bladder cancer progression." (PMID 29100339, 2017). "In addition to that, we demonstrated that metformin inhibits bladder cancer cell growth and enhances apoptosis by downregulating cyclinD1 and Bcl-2." (PMID 27058422, 2016). "Furthermore, overexpression of miR-192 significantly induced apoptotic death in bladder cancer cells, increased the levels of p21, p27, and Bax, and decreased the levels of cyclin D1, Bcl-2, and Mcl-125." (PMID 27577949, 2016). "PLCE1 silencing may also downregulate MMP and BCL2 gene expression, thereby reducing the invasiveness of bladder cancer cells." (PMID 26657507, 2016). "The Bax-Anti Bcl2 combination module driven by artificial hTERT promoter could availably and selectively over-express Bax gene and interference sequence of Bcl2 to reverse the ratio of Bcl2/Bax for intervention of malignant phenotype of bladder cancer cells." (PMID 26743236, 2016). "Finally, the artificial hTERT promoter-Bax-Anti Bcl2 combination module was constructed and tested in the bladder cancer cells and normal human fibroblasts." (PMID 26743236, 2016). "Base on the confirmed high efficiency and specificity of artificial hTERT promoter, artificial hTERT promoter-Bax-Anti Bcl2 combination module has been constructed to determine whether this module selectively inhibits cell proliferation in bladder cancer." (PMID 26743236, 2016). "In this study, we constructed the Bax-Anti Bcl2 combination module driven by artificial hTERT promoter which could over express Bax and knockdown of Bcl2 and tested the ability of this module in selectively indentifying and killing bladder cancer cells." (PMID 26743236, 2016). "Moreover, qRT-PCR results revealed that three STAT3 direct target genes (bcl2, bclxl and mcl1) were downregulated at mRNA levels in both two bladder cancer cell lines, indicating that the reduction is mainly due to the transcriptional regulation." (PMID 25849286, 2015). "The mRNA expression ratio of Bcl-2/Bax in tumoral bladder tissues mayserve as a significant prognostic indicator in predicting the clinical outcome in low gradenon-invasive bladder cancer." (PMID 24381861, 2014). "The treatment of the bladder cancer cells with 1.5 μM sanguinarine did not cause significant changes in the expression of the antiapoptotic proteins Bcl-2 and Bcl-xL." (PMID 23717422, 2013). "We have previously demonstrated that quantification of the antiapoptotic protein BCL2 in patients undergoing neoadjuvant chemotherapy plus radiotherapy for advanced bladder cancer may identify patients who might benefit from neoadjuvant chemotherapy." (PMID 12592374, 2003). "Finally, we explored whether cell apoptosis of bladder cancer cells were selectively induced by artificial hTERT promoter-Bax-Anti Bcl2 combination module." (PMID 26743236, 2016).